LINC00299 (long independently transcribed non-coding RNA 299)
Synonyms: C2orf46; NCRNA00299; FLJ45673; LINC00298; LINC01814
Gene: Long non-coding RNA gene on chromosome 2 (7,922,425 to 8,595,477, reverse strand). Ensembl gene ENSG00000236790.
Diseases named in the same sentence as LINC00299 in open-access papers:
LINC00299 is named in the same sentence as 5 diseases in open-access papers, as found by Europe PMC text mining. Sharing a sentence is not in itself a finding about the gene and the disease. The quoted sentences say what the papers report.
atherosclerosis (1 paper, 2022). A disease characterized by the build-up of fatty material and calcium deposition in the arterial wall resulting in partial or complete occlusion of the arterial lumen. "In atherosclerosis, the expression of LINC00299 is upregulated, promoting migration and proliferation, and alleviating apoptosis of vascular smooth muscle cells by sponging miRNAs." (PMID 36226317, 2022).
neurodevelopmental disabilities (1 paper, 2022). "Additionally, LINC00299, located on chromosome 2, is abundantly expressed in the brain and related to neurodevelopmental disabilities." (PMID 36226317, 2022).
LINC00299 also shares sentences with these, for which no sentence is quoted: asthma (1 paper); breast carcinoma (1); gastric cancer (1).